TCF4 (transcription factor 4)
Diseases named in the same sentence as TCF4 in open-access papers (continued):
Sharing a sentence is not in itself a finding about the gene and the disease.
fragile X-associated tremor/ataxia syndrome (1 paper, 2019). Fragile X-associated tremor/ataxia syndrome (FXTAS) is a rare neurodegenerative disorder characterized by adult-onset progressive intention tremor and gait ataxia. "In our analysis, TCF4 was noticed to activate fragile X mental retardation 1 (FMR1) gene, which is associated with the neurodegenerative condition such as Fragile X-associated tremor ataxia syndrome (FXTAS)." (PMID 31484947, 2019).
gastrointestinal carcinoma (1 paper, 2017). "In human gastrointestinal carcinoma, defects in the Wnt-APC pathway results in enhanced T-cell factor 4 (TCF4) transcriptional activation of c-MYC." (PMID 29232378, 2017).
generalized dystonia (1 paper, 2022). "In eight patients with generalized dystonia from infancy, the mutation of PIGA, TCF4, CHRNG, SLC16A2, KCNQ2, NACC1, CTNNB1, or ARSA gene were found to be causative." (PMID 35719373, 2022).
glomerulonephritis (1 paper, 2023). A renal disorder characterized by damage in the glomeruli. "Mice overexpressing TLR7 from a BAC Tg had ameliorated glomerulonephritis and reduced germinal centers when pDC function was impaired via haploinsufficiency of Tcf4, implying a role for pDCs." (PMID 37606042, 2023).
hypertriglyceridemia (1 paper, 2015). A laboratory test result indicating elevated triglyceride concentration in the blood. "Minor alleles of the gene encoding the canonical Wnt transcription factor TCF4 have been associated with reduced expression of TCF4 and hypertriglyceridemia among relatives with familial combined hyperlipidemia." (PMID 26046396, 2015).
immunodeficiencies (1 paper, 2024). "Mouse data and studies on patients with combined immunodeficiencies highlighted the role of the transcription factors TCF4 (also known as E2-2), IRF8 and Ikaros family zinc finger 1 (IKZF1) for pDC differentiation." (PMID 38504978, 2024).
intestinal polyposis (1 paper, 2021). "fl-Tcf4 and dnTcf7 transcripts are the predominant Tcf/Lef1 family isoforms expressed in the intestine, which explains the opposite intestinal phenotypes in mice deleted of Tcf7l2 (lack of cycling stem cells) versus Tcf7 (intestinal polyposis)." (PMID 34788095, 2021).
liposarcoma (1 paper, 2012). A usually painless malignant tumor that arises from adipose tissue. "The beta-catenin/TCF4 pathway also modifies alternative splicing through modulation of expression of splicing factors SRp20 and SF1 and direct interaction with FUS/TLS (translocated in liposarcoma) and various other RNA-binding proteins, including p54nrb." (PMID 22682314, 2012).
mesenchymal neoplasm (1 paper, 2025). "Herein, we present a case of an acral chondromyxoid mesenchymal neoplasm harboring a novel in-frame TCF4::ERG fusion involving the right index finger of a 26-year-old female." (PMID 40878874, 2025).
metastatic cancer (1 paper, 2023). A carcinoma which has spread from the original site of growth to another anatomic site. "Results revealed a higher Mesenchymal markers in primary cancer cells (e.g., NCAM1, LAMB1, SERPINE1, TCF4, VIM, ZEB1, and ZEB2) and a higher Epithelial markers in metastatic cancer cells (e.g., CDH1, CLDN4, ELF3, EPCAM, KRT18, KRT7, and KRT8)." (PMID 37202394, 2023).
metastatic melanoma (1 paper, 2023). A melanoma that has spread from its primary site to another anatomic site. "In the current study, we elucidated a novel mechanism involved in VM development, connecting VE-Cad/ β-catenin/TCF-4 expression with the induction of VM in metastatic melanoma cells." (PMID 36797281, 2023).
myeloid leukemia (1 paper, 2014). A clonal proliferation of myeloid cells and their precursors in the bone marrow, peripheral blood, and spleen. "We also observed downregulation of transcription factors such as Mga and Tcf4, and myeloid leukemia related genes including Pml, Abl1, and Bcl11a in terminally differentiated granulocytes in conjunction with the expression of a group of granulocyte-enriched miRNAs." (PMID 24886830, 2014).
myeloproliferative neoplasm (1 paper, 2020). A clonal hematopoietic stem cell disorder, characterized by proliferation in the bone marrow of one or more of the myeloid (i.e., granulocytic, erythroid, megakaryocytic, and mast cell) lineages. "Additionally, increased TCF4 transcriptional activity contributes to the pathogenesis of transformation of post-myeloproliferative neoplasms into secondary AML, which is related with the abnormal activation of wnt/β-catenin signaling." (PMID 32714094, 2020).
Paranoia (1 paper, 2014). The feeling and belief that one is being targeted or is a focus of negative or untoward actions, overt or covert, from others. "The strongest association was observed between the SPEQ Paranoia psychotic experiences subscale and rs17512836 in TCF4 with C identified as the risk allele." (PMID 24718684, 2014). "In addition, association between rs9960767 in TCF4 and Paranoia was significant in the genotypic test (prawdata = 4.44×10−5; pEMP = 9.33×10−4; ptransformeddata = 6.23×10−4; pEMP = 0.005)." (PMID 24718684, 2014).
Pruritus (1 paper, 2022). Pruritus is an itch or a sensation that makes a person want to scratch. "We identified several pruritus-associated genes increased by IDL, IDC and IDL + IDC (e.g., BRCA2, KRT5, TCF4), as well as several such genes decreased by IDL, IDC and/or IDL + IDC (e.g., IL2RG, TRPV3, TNFSF15, IL17RC)." (PMID 36430783, 2022).
rectal cancer (1 paper, 2016). A primary or metastatic malignant neoplasm that affects the rectum. "Additionally, previous literature has revealed that TCF3 and TCF4 are overexpressed in rectal cancer and they control MYC expression in colorectal cells." (PMID 27818995, 2016).
renal carcinoma (1 paper, 2023). A carcinoma arising from the epithelium of the renal parenchyma or the renal pelvis. "For example, FOXO1‐H215R induced the related WNT pathway component TCF4 in renal carcinoma cells; this gene was also increased in our RNA‐Seq data by AS1842856 treatment (P = 1.25E‐38)." (PMID 37584250, 2023).
sarcoma (1 paper, 2021). A usually aggressive malignant neoplasm of the soft tissue or bone. "In summary, our work shows that EMX1 and EMX2 act as tumor suppressors by suppressing the activity of stem cell regulatory genes (OSKM, NANOG, and PROM1) and effectors of the canonical Wnt pathway (CTNNB1, TCF4, MYC, WNT1 and CCDN1) in sarcoma." (PMID 34364391, 2021). "In sarcoma cells, we found reductions in the protein levels of positive effectors of the Wnt pathway (β-catenin, TCF4, c-MYC and WNT1) and increases in those of negative effectors (GSK3-β and AXIN1) in cells overexpressing EMX proteins." (PMID 34364391, 2021).
Sepsis (1 paper, 2024). Sepsis is defined as life-threatening organ dysfunction caused by a dysregulated host response to infection. "It was noted that several genes with DRE were previously reported or implicated to play a role in sepsis or SAE, such as superoxide dismutase 2 (SOD2), Miat, peptidylarginine deiminase 2 (Padi2), Shank1, transcription factor 4 (Tcf4) and kinesin family member 3 (Kif3c)." (PMID 39135964, 2024).
skin inflammation (1 paper, 2024). "Ear skin of KC-Tie2 mice treated with Tcf4 siRNA developed decreases in epidermal TCF4 expression and worsened skin inflammation compared with control siRNA–treated ear skin, including increases in epidermal thickness and CD3+ T cell staining." (PMID 38470486, 2024). "This demonstrated that Tcf4 negatively regulated Il17c and Zc3h12a in vivo to promote skin inflammation." (PMID 38470486, 2024). "TCF4 expression negatively corresponds to skin inflammation in an IL-17C–IL-17RA/RE–dependent manner." (PMID 38470486, 2024). "The increases in TCF4 in these mice further validate the capacity for skin inflammation to regulate TCF4 expression, with KC data suggesting that TNF-α, IL-17A, and IL-17C likely contribute to regulating (decreasing) TCF4." (PMID 38470486, 2024). "To demonstrate that TCF4 directly affects skin inflammation in vivo, we used a topical delivery method of siRNA to decrease Tcf4 gene expression." (PMID 38470486, 2024). "Moreover, interference with cutaneous TCF4 using topical application of Tcf4 siRNA worsens skin inflammation by increasing cutaneous Il17c and Zc3h12a and by increasing skin infiltrating CD3+ T cell numbers, resulting in worsened acanthosis." (PMID 38470486, 2024). "Whether TCF4 contributes to skin inflammation has not been examined." (PMID 38470486, 2024). "A negative TCF4/IL-17C/ TNF-a/ IL-17A feedback loop decreases TCF4 in an IL-17RA/RE-dependent manner and is further amplified by IL-17C/TCF4 regulation of ZC3H12A and IL-17C regulation of NFKBIZ, resulting in self-sustaining skin inflammation." (PMID 38470486, 2024).
sleep disorder (1 paper, 2025). A change from the patient's baseline sleeping pattern, in the hours slept and/or an alteration/dysfunction in the stages of sleep. "We observed 142 associations including at known loci for sleep disorders (e.g. MEIS1, CACNA1C, OLFM4, PAX8 and TCF4)." (PMID 41332830, 2025).
small intestinal tumors (1 paper, 2018). "In fact, concomitant deletion of Tcf4 and Apc resulted in a significant decrease in the size of small intestinal tumors." (PMID 30200414, 2018).
Splenomegaly (1 paper, 2018). Abnormal increased size of the spleen. "Overall, apart from decreased splenomegaly, Tcf4 haplodeficiency had no impact on the general immune activation caused by Was-deficiency." (PMID 30410494, 2018).
steatosis (1 paper, 2016). Increased lipid within the cytoplasm of cells. "Increased expression levels of phospho-GSK-3β, β-catenin and TCF4 induced by exendin-4 treatment were observed in an in vitro model of steatosis." (PMID 27907035, 2016).
T-cell leukemia (1 paper, 2020). A malignant disease of the T-lymphocytes in the bone marrow, thymus, and/or blood. "In adult T-cell leukemia, TCF4 up-regulates BIRC5 expression, which probably increase the viability of cell viability." (PMID 32714094, 2020).
thymoma (1 paper, 2022). A neoplasm arising from the epithelial cells of the thymus. "In contrast, levels of nuclear inhibitors were variably higher in thymomas and TCs than in NTs: TLE2 and TCF4 were significantly (p <0.01) higher in B3 thymomas and TCs, TLE4 only in B3 thymomas and TCF3 only in AB thymomas." (PMID 35965500, 2022).
thyroid cancer (1 paper, 2025). "As for the lncRNA EGFEM1P, it was reported that it promotes thyroid cancer progression by acting as an miR−369−3p sponge and upregulating TCF4." (PMID 40552117, 2025). "EGFEM1P was also reported to be upregulated in papillary thyroid tumors and thyroid cancer cells compared with normal adjacent tissues, and promoted thyroid cancer progression by acting as an miR-369-3p sponge and upregulation TCF4." (PMID 40552117, 2025).
type 1 diabetes (1 paper, 2018). "Tcf4 haplodeficiency and conditional targeting were also shown to ameliorate the development of SLE and type 1 diabetes in vivo, confirming key roles for pDCs in such pathologies." (PMID 30410494, 2018).
ulcerative colitis (1 paper, 2025). An inflammatory bowel disease involving the mucosal surface of the large intestine and rectum. "Notably, impaired intestinal mucosal barrier, an important feature of ulcerative colitis, is usually associated with targets such as protein kinase B (AKT1), nuclear factor-κB (NF-κB), transcription factor 4 (TCF-4), mitogen-activated protein kinase (MAPK), etc.." (PMID 41154516, 2025).
tumor (252 papers, 2005 to 2026). "Using conditional alleles of Tcf7l2 and Apc in combination with Defa6-iCre, we were able to analyze the effects of Tcf4 loss on a subpopulation of cells within the developing tumor." (PMID 40221753, 2025). "This was confirmed, enabling us to use this mouse line to inactivate Tcf7l2 in tumor cells and study the effects of Tcf4 loss on their development." (PMID 40221753, 2025). "Our functional analysis demonstrated that loss of TCF4 dramatically decreased cell proliferation, induced apoptosis, and inhibited tumor growth in vivo." (PMID 39119816, 2025). "The inhibition of TCF4 directly caused Endoplasmic Reticulum stress dysregulation and promoted tumor cell death." (PMID 37337284, 2023). "TCF4 is known as a tumor suppressor in some cancer types: In coloncancer, loss of TCF4 leads to tumorigenesis via dysregulation ofproliferation andmetastasis, and inmedulloblastoma, in vitro over-expression of TCF4 suppressed cellproliferation and growth." (PMID 38100720, 2023). "HOXB13 suppresses wnt/β‐catenin signalling in colon cancer, hence exhibiting a tumour suppressor function in this context, but does so through inhibiting transcription of the TCF4 gene (the product of which encodes a cofactor for β‐catenin)." (PMID 35080776, 2022). "Next, to determine the role of TAMs recruitment and M2 polarization in tumor growth, we have evaluated the Ki67 expression in TCF4 deficient and control tumors by immunohistochemistry and Q-PCR." (PMID 34580284, 2021). "Previous studies have demonstrated that TCF4 alternative splicing shows underlying tumor-promoting properties in various malignancies." (PMID 34215252, 2021). "Sequencing analysis confirmed 5/60 patients with a point mutation in exon 1 of the TCF-4 gene in tumor samples." (PMID 32265994, 2020). "Our findings demonstrated for the first time the presence of mutations in exon 1 along with decreased expression of TCF-4 gene/protein in tumor tissues compared to normal and adjoining mucosa." (PMID 32265994, 2020). "Adenomatous polyposis coli (APC) or β-catenin gene mutations lead to increased tumor incidence through the stabilization of β-catenin and transcriptional activation with TCF-4, which play a pivotal role in CRC." (PMID 29464031, 2018). "Changes in TCF4 expression have been linked to tumor progression through stimulation of the Wnt pathway." (PMID 29212479, 2017). "Loss of LEF1 and gain of TCF4 expression is associated with tumor progression involving a change from proliferative to an invasive phenotype." (PMID 25763355, 2015). "TCF4 mutations have been reported in primary CRCs and its loss induces cell proliferation suggesting a possible role as a tumor suppressor." (PMID 24943349, 2014). "TCF4 is the main binding partner of β-catenin in the colon and mediates transformation of colon epithelial cells upon loss of the tumour-suppressor protein APC." (PMID 21092222, 2010). "Next, we investigated the effects of Tcf4 deficiency in tumor cells expressing Defa6-iCre." (PMID 40221753, 2025). "After the loss of Tcf4, these cells take on the characteristics of goblet cells and lose the expression of α-defensin, which can subsequently affect the characteristics of the tumor and its interaction with the colon microbiome." (PMID 40221753, 2025). "Moreover, overexpression or silencing of TCF4 caused a decrease or increase in the level of ROS and Ca2+ in tumor cells and caused aggregation, tightening, or expansion and swelling of the Endoplasmic Reticulum morphology." (PMID 37337284, 2023). "Meanwhile, the M2/M1 ratio in TCF4 deficient tumors was decreased compared with the control tumor." (PMID 34580284, 2021). "The formation of this complex could be blocked by ICG-001 or LF3, an inhibitor of interaction between β-catenin and TCF4, which resulted in the loss of the capacity of tumor propagating cells for self-renewal and reduced tumor formation in vivo." (PMID 32183420, 2020).
tumor (continued). "Adult Group 4 tumours harboured recurrent mutations in TCF4 and chromatin modifier genes." (PMID 33172502, 2020). "Although most targets of MMR deficiency are considered to be tumor suppressor genes that through the frameshift outcome lose their function there are also studies showing activating mutations such as the frameshifts in the TCF4 gene." (PMID 27907910, 2017). "In multivariate analysis, LEF-1 and TCF4 expression were confirmed to be independent predictors of longer respectively shorter overall survival, when considered together with tumour stage, gender and age (risk ratio for LEF-1: 2.66; p = 0.027 risk ratio for TCF4: 2.18; p = 0.014)." (PMID 21092222, 2010). "This leads to the establishment of a VE-Cadherin/β-catenin/TCF-4 signaling axis, thereby enhancing the ability of tumor cells to form vessel-like structures." (PMID 41019994, 2025). "Our results reveal that TCF4 knockdown counteracts the tumor-promoting effects of circ_0000467, suggesting that circ_0000467 enhances CRC malignancy by modulating the miR-520g/TCF4 axis." (PMID 40290725, 2025). "This raises important questions: What is the role of these Paneth-like cells in tumor biology, and how does Tcf4 influence their identity and function?" (PMID 40221753, 2025). "Elevated ROS levels in the tumor microenvironment increase exogenous cystine/cysteine uptake by activating transcription factor 4 (ATF4) to maintain elevated intracellular cysteine levels in CRC and support tumor growth." (PMID 40075600, 2025). "In the context of EC, LINC00958 has been shown to promote tumor progression through modulation of the miR‐145‐3p/TCF4 axis." (PMID 41090505, 2025). "Nuclear β-catenin can bind to TCF4 and costimulate the transcription of target genes to promote tumor progression." (PMID 41213915, 2025). "Molecular interactions with miR-520g and TCF4 were examined, and in vivo experiments assessed tumor growth." (PMID 40290725, 2025). "Another cell cycle regulator, EZH2, which is involved in epigenetic silencing of tumor‐suppressor genes by H3K27 methylation was identified as a putative direct target of TCF4." (PMID 39119816, 2025). "TCF4, a crucial transcription factor in the Wnt/β-catenin pathway, interacts with β-catenin to drive tumor progression." (PMID 40290725, 2025). "In cancer ZEB1 is an epithelial-to-mesenchymal (EMT) transition activator, and the TCF4/ β-catenin complex induces ZEB1 to regulate tumor invasiveness." (PMID 40961119, 2025). "In vivo, CAFs promoted CRPC tumor growth and significantly increased the expression of Wnt3a, β-catenin, TCF4, LEF1, SDF-1, and CXCR4, along with an elevated p-GSK-3β/GSK-3β ratio." (PMID 40735647, 2025). "We found that decreased expression of TCF4 in Kelly and SK‐N‐AS cells delayed tumor growth in vivo, as reflected in the mean tumor volume over time compared with the control in both cell lines." (PMID 39119816, 2025). "TARBP2 plays a role in microRNA biogenesis of miR-1306 and miR-33a, which exert tumor suppressive roles by co-targeting TCF4 in GC." (PMID 38806480, 2024). "In order to explore the anti-tumor effect of MGST1 knockdown, we utilized LF3 and PKF-118-310, two antagonist of the β-catenin/Tcf4 complex that possesses anti-tumor properties." (PMID 39501138, 2024). "According to a study, a bromine domain and extra terminal domain inhibitor can induce tumor cell apoptosis by disrupting the specific transcription network that the TCF4 TF regulates." (PMID 38273392, 2024). "SNAI1 also known as ZEB2 (zinc finger E-box binding homeobox 2), as well as ZEB1, E2-2 (as also known as transcription factor 4) and Twist, were all up-regulated in ECSs, similar to other tumor types." (PMID 38836981, 2024). "Neuronal markers (targets of β-catenin-TCF4, ref#29) are significantly increased in the tumor sections." (PMID 39796711, 2024).